CSF1 (colony stimulating factor 1)
Diseases named in the same sentence as CSF1 in open-access papers (continued):
Sharing a sentence is not in itself a finding about the gene and the disease.
glioma (continued). "An autochthonous glioma model, with characteristics of the proneural subtype of human high-grade gliomas, also emphasized the importance of CSF-1 signalling in de novo gliomagenesis, with CSF-1 overexpression significantly increasing the formation of high-grade gliomas." (PMID 33803414, 2021). "CCL2, produced in the glioma microenvironment, is essential for the recruitment of regulatory T cells and myeloid-derived suppressor cells, as well as macrophages that are dependent on colony stimulating factor-1 (CSF-1) for both differentiation and survival." (PMID 34394072, 2021). "Furthermore, microglia produce IGFBP1 in response to glioma-derived CSF1, and IGFBP1 has been shown to induce angiogenesis in glioma cells." (PMID 34503065, 2021). "Accordingly, targeting the CSF-1/CSF-1R axis may represent a potential therapeutic approach in glioma." (PMID 34950148, 2021). "In addition, CSF-1 was extensively reported in glioma, involving in ionizing radiation resistance, high-grade of glioma, cell proliferation and invasion." (PMID 34627193, 2021). "The importance of CSF-1 in glioma been shown in a separate glioma model; where inhibition of CSF-1 results in the complete destruction of the tumor presumably by inducing the repolarization of TAMs from a trophic (“M2”) state to a proinflammatory state (“M1”) and thus reversing immunosuppression." (PMID 34843542, 2021). "Besides, CSF-1 overexpression promoted glioma cell viability and metastasis, while CSF-1 knockdown presented the opposite effects." (PMID 34627193, 2021). "The crosstalk between GAMs and tumour cells via CSF-1 can indirectly regulate glioma development." (PMID 33803414, 2021). "Next, Base on the TCGA data, we found high expression of CSF‐1 in glioma." (PMID 31994318, 2020). "We could discern miR‐1254 as a primary mediator of proliferation in glioma that targets CSF‐1 directly." (PMID 31994318, 2020). "The outcome revealed that CSF‐1 overexpression promoted glioma cell propagation." (PMID 31994318, 2020). "MiR-532-5p inhibits glioma cell proliferation by targeting colony-stimulating factor 1 (CSF1)." (PMID 32677950, 2020). "Our newly confirmed miR‐1254/CSF‐1 axis aids in delving into the mechanisms of glioma development and may help formulating more robust molecular targeting therapy for human gliomas." (PMID 31994318, 2020). "Indeed, CSF‐1 overexpression reduced the rate of apoptosis, while of CSF‐1 inhibition enhanced the apoptosis of glioma cells, which was disrupted by anti‐miR‐1254." (PMID 31994318, 2020). "After migrating into the glioma environment, TAMs tend to possess the M2 phenotype, and their differentiation is driven by the secretion of immunosuppressive factors, including CSF-1, CCL2, IL-4, IL-6, IL-10, and transforming growth factor (TGF- β), from tumor cells." (PMID 30619286, 2018). "CSF-1 (M-CSF) secreted by glioma cells facilitates recruitment and M2-like activation of GAMs." (PMID 29389898, 2018). "Importantly, however, anti‐CSF‐1 therapy also seemed to improve the access of the standard‐of‐care chemotherapy temozolomide to gliomas, with a significant increase in median survival when compared to chemotherapy alone." (PMID 29127101, 2017). "Mathivet and coworkers then employed an anti‐CSF‐1 antibody to target the TAMs in gliomas." (PMID 29127101, 2017). "In order to analyze the specificity of vessel dilation for glioma and its link to myeloid cell recruitment in the tumor microenvironment, we inoculated B16 melanoma in the flank of wild‐type mice and depleted macrophages using anti‐CSF1 mAb treatment." (PMID 29038312, 2017). "Similarly, colony stimulating factor-1 (CSF-1) creates a supportive glioma microenvironment, such that silencing CSF-1-receptor signaling on macrophages is sufficient to reduce high-grade glioma growth in mice." (PMID 28380429, 2017).
glioma (continued). "In our hands, targeting macrophage recruitment in the glioma microenvironment with anti‐CSF1 treatment or decreasing macrophage VEGF production similarly accelerate tumor growth, but restore a functional and perfused blood vessel network that can support effective delivery of anti‐tumoral drugs." (PMID 29038312, 2017). "In addition, recombinant CSF1 treatment significantly delayed glioma growth (52% size reduction) compared to control and anti‐CSF1 antibody treatment." (PMID 29038312, 2017). "Diverse immunomodulators and immunosuppressive factors are secreted by glioma cells, for example, interleukin-6 (IL-6) and colony stimulating factor-1 (CSF-1), which play an important role in Th2 response; this enhances its activity resulting in a less effective response against tumors." (PMID 27294132, 2016). "Cloning insertions from these SB-induced gliomas identified Sfi1, Csf1, Mkln1, Vps13a and Fli1 as common insertion sites (CISs) which are chromosomal regions that are insertionally mutated in more tumors than would be expected by random chance and represent candidate glioma genes." (PMID 25423036, 2014). "DHX9/TCF12/CSF1 axis regulated the increases in the infiltration of TAMs to promote glioma progression and might be a novel potential target for future immune therapies against gliomas." (PMID 36377508, 2023). "Additionally, glioma cells implanted into irf8−/− transgenic zebrafish that lack microglia and wild-type zebrafish treated with CSF-1 inhibitor (a pharmacological means of decreasing microglia) have demonstrated a unique role for zebrafish microglia in facilitating human glioma cell growth." (PMID 33644052, 2021). "Thus, the results indicate a noticeable inhibitory effect of miR‐1254 on CSF‐1 and therefore may possibly act as therapeutic options for glioma patients." (PMID 31994318, 2020). "Thus, we investigated the effect of miR‐1254/CSF‐1 axis on glioma." (PMID 31994318, 2020). "Therefore, the use of CSF1R and CSF1 inhibitors in glioma might have differential effects, as the downstream signaling events triggered by CSF1 and IL‐34 are distinct." (PMID 29038312, 2017). "Thus, blocking CSF-1 or IL-34 signaling by inhibition of the common receptor CSF-1R could be an innovative treatment strategy, as shown in the glioma model." (PMID 26098772, 2015). "The elevated levels of CSF1 derived from hybrid cells reprogram the glioma TME by modulating macrophages, consequently promoting glioma progression." (PMID 40287444, 2025). "Overall, these findings indicate that the fusion of GA-MSCs with glioma cells promotes macrophage recruitment and M2-like polarization through FTO-mediated CSF1 secretion within the TME." (PMID 40287444, 2025). "TAM-directed therapies using CSF-1 and CSF1R inhibitors have been tested in preclinical models of gliomas, as well as in clinical studies." (PMID 37509400, 2023). "Several factors, including STI1, EGF, CSF-1, CCL2, IL-6, TGF-β and TGF-β2, are released from TAMs and can promote glioma proliferation and/or migration." (PMID 37705736, 2023). "Chemoattractants such as MCP-1 (CCL2), MCP-3 (CCL7), SDF-1 (CXCL12), CX3CL1, POSTN, GM-CSF, M-CSF (CSF-1) and EGF produced by glioma cells actively recruit TAMs and thus promote tumor growth." (PMID 37705736, 2023). "In conclusion, we demonstrated that DHX9 was elevated in gliomas and promoted the proliferation, migration, invasion of glioma cells, and the infiltration of TAMs by targeting the TCF12/CSF1 axis." (PMID 36377508, 2023). "Tumor-derived macrophage colony stimulating factor (M-CSF, CSF1) and granulocyte macrophage colony stimulating factor (GM-CSF, CSF2) induce microglia accumulation and activation, as well as glioma progression." (PMID 34439380, 2021). "Gliomas have been shown to actively recruit TAMs by releasing several factors, including SDF-1 (CXCL12, C-X-C Motif Chemokine Ligand 12), and M-CSF (CSF-1; Colony Stimulating Factor 1)." (PMID 32570988, 2020).
glioma (continued). "In summary, recruitment and subsequent M2 polarization of GAMs has been shown to be mediated by multiple glioma cell-derived chemoattractants such as MCP-1 (CCL2), SDF-1 (CXCL12), M-CSF (CSF-1), GM-CSF, and EGF." (PMID 29389898, 2018). "As previously discussed, glioma and microglia interactions mediated through EGF and CSF-1 can also increase tumor invasion." (PMID 23864876, 2013). "Interestingly, we found that most of these ligands (e.g., CSF1, CXCL8, POSTN) 21, 32, 43 are broadly expressed in different glioma subclusters, whereas SPP1 is specifically expressed in the CEBPB+ GBM subcluster." (PMID 38994023, 2024). "TAMs produce many proteins that can enhance glioma proliferation and/or migration, such as stress-inducible protein 1 (STI1), epidermal growth factor (EGF), colony-stimulating factor 1 (CSF-1), chemokine ligand 2 (CCL2), interleukin-6 (IL-6), and transforming growth factors: TGF-β and -β2." (PMID 39452154, 2024). "Non-neoplastic astrocytes also contribute to glioma progression by expressing tumor-promoting proteins such as TGF-ß, STAT3, CCL2 and CSF1 in later tumor stages after causing initial astrogliosis at the tumor boundary in earlier tumor stages." (PMID 38275375, 2023). "Flow cytometry analysis presented that when cocultured with si‐DHX9 glioma cells, the ratio of CD68+/CD163+ cells were significantly lower than the control; however, this effect could be partly reversed by cocultured with CSF1 overexpressed glioma cells." (PMID 36377508, 2023). "On the other hand, glioma-cells release chemoattractant molecules that recruit TAMs and promote tumor growth: CCL2, CCL7 (or MCP-3), IL-33, GDNF (Glial cell line-derived neurotrophic factor), MCP-1 (CCL2), SDF-1 (CXCL12), CSF-1 (M-CSF), GM-CSF, and EGF." (PMID 35269652, 2022). "In conclusion, CSF1 and CSF2 are important factors involved in TAM recruitment and glioma progression and, therefore, the inhibitors of CSF1 and CSF2 signaling could be further explored for their potential beneficial effects in GBM." (PMID 34439380, 2021). "Regarding CSF-1R/CSF-1 axis as a target for therapy, we have demonstrated that CSF-1R inhibition by PLX3397 affected more M2 than M1 macrophages, and induces their repolarization towards an M1-like phenotype, in accord with published results in glioma." (PMID 33731849, 2021). "The glioma microenvironment is enriched with inflammatory mediators/chemotactic factors such as monocyte chemoattractant proteins (MCP-1, -3), glial cell-derived neurotrophic factor (GDNF), and colony-stimulating factor (CSF-1, -2)." (PMID 34439380, 2021). "Glioma cells release chemo-attractans, such as monocyte chemo-attractant protein-1 (MCP-1), fractalkine (CX3CL1), glial cell–derived neurotrophic factor (GDNF), and colony stimulating factor-1 (CSF)-1) that recruit GAMs to tumor tissue." (PMID 31467533, 2019). "Gliomas help recruit TAMs to the TME by secreting various chemokines, including monocyte chemoattractant proteins (MCP-1/CCL2 and MCP-3), C-X-C motif chemokine 12 (CXCL12), colony-stimulating factor 1 (CSF-1), lysyl oxidase (LOX), and glial cell-derived neurotrophic factor (GDNF)." (PMID 38254796, 2024). "CSF-1/CSF-1R is the essential signaling pathway for macrophage survival and proliferation, but the CSF-1R inhibitor BLZ945 suppresses glioma growth and progression by altering macrophage polarization, but not by depleting macrophages 104, and improves the survival rate of glioma mice." (PMID 37705736, 2023). "The role of the CSF-1/CSF-1R axis in tumor progression is of great importance not just for glioma." (PMID 34843542, 2021). "In a murine glioma model where Csf1 expression is increased approximately 2.5-fold compared to normal brain, CSF1R inhibitors decrease expression of M2 markers including Arg1 in GAMs, suggesting that increased CSF1/CSF1R signaling can promote polarization toward a M2 phenotype in the diseased CNS." (PMID 34281564, 2021).
glioma (continued). "Therefore, a negative correlation exists between CSF‐1 and miR‐1254 with respect to their effects on functions of glioma cells." (PMID 31994318, 2020). "CSF1/M-CSF signalling maintains proliferation and survival of monocytes through DAP12-β-catenin signalling pathway, and CSF2/GMCSF has been shown to regulate β-catenin signalling during myeloid lineage differentiation, and contribute to the survival of infiltrating monocytes in rat gliomas." (PMID 32390004, 2020). "Therefore, a negative relationship exists between CSF‐1 and miR‐1254 and their contrasting effects on initiation and advancement of glioma." (PMID 31994318, 2020). "Depletion of macrophages using anti‐CSF1 strategy or genetic depletion of macrophage‐derived VEGF‐A production normalized vascular patterning and restored vessel functionality, substantially improving chemotherapeutic agent efficacy and survival in glioma‐bearing mice." (PMID 29038312, 2017). "While glioma cell-derived CSF1 plays a critical role for the differentiation and survival of TAMs, TAM derived EGF may contribute to the high EGFR signaling in the gliomas cells, even in the absence of mutations within the EGFR gene or amplification of this region." (PMID 27385209, 2016). "Then, the expression of CSF1 in these cells was assessed by qRT‐PCR, which showed that the DHX9‐overexpression plasmid failed to upregulate CSF1 in si‐TCF12‐transfected glioma cells." (PMID 36377508, 2023). "Furthermore, CSF-1 also regulates glioblastoma aggressiveness, with histological analysis of CSF-1R inhibitor-treated tumours revealing grade II and III glioma features, as opposed to the grade IV glioblastoma features seen in vehicle-treated mice." (PMID 33803414, 2021). "Interestingly, IL-6, but not CSF-1, was preferentially localized in CD31+ ECs, implying that ECs as a major source for the expression of IL-6 but not CSF-1 in glioma microenvironment." (PMID 29422647, 2018).
COVID-19 (84 papers, 2020 to 2025). A disease caused by infection with severe acute respiratory syndrome coronavirus 2. "Using machine learning, we identified a set of diagnostic plasma biomarkers (e.g., TRIM21, CASP8, PTN and CSF1) that had very high accuracy in differentiating COVID-19 from CAP, and outperformed standard laboratory parameters used in clinical practice." (PMID 36829233, 2023). "Consistently, it has been recently reported that T-cell derived CSF-1, acting via intercellular crosstalk, may be associated with cytokine storm in COVID-19." (PMID 33194826, 2020). "While the CSF1 gene increased in the NP group, it showed a significant decrease in severe COVID-19 patients." (PMID 39205185, 2024). "The myocardial injury caused by COVID-19 was associated with multiple inflammatory pathways, and IL6, NFKBIA, CSF1, CXCL1, IL1R1, SOCS3, and CASP1 were key genes of the inflammatory pathway." (PMID 37564653, 2023). "CSF1 was already identified as a biomarker involved in the main biological processes leading to severe COVID-19 manifestations and was assumed to reflect levels of lung inflammation." (PMID 37041310, 2023). "Only OPG and colony-stimulating factor-1 (CSF-1), related to severe COVID-19, were significantly higher in women." (PMID 34434199, 2021). "In the lungs, COVID-19 causes lung dysfunction by regulating the expression of SRC, RHOA, CD40LG, CSF1, and TNFRSF1A." (PMID 34504502, 2021). "Although these proteins were not differentially abundant in lung tissue in our study, macrophage colony stimulating factor (M-CSF/CSF-1), a key driver of proliferation and differentiation of monocytes, macrophages, and their precursors, was increased in COVID-19 splenic tissue." (PMID 34710339, 2022). "Macrophage CSF-1 was also increased in abundance in COVID-19 splenic tissue." (PMID 34710339, 2022). "CSF1 enhances macrophage recruitment and activation and its overexpression may contribute to the acute inflammatory response observed in severe COVID-19." (PMID 33194826, 2020). "Several inflammatory mediators, such as ENPP2, C5, FASLG, VWF, and CSF1, additionally presented a more robust correlation with the core inflammatory networks in the severe group, and these factors were reported as independent significant indicators of severe COVID-19 in previous studies." (PMID 36776879, 2023). "Previous studies reported that COVID-19 is frequently associated with a massive production of 14 cytokines including IFN-γ, IL-1RA (IL1RN), IL-2RA, IL-6, IL-10, IL-18, HGF, MCP-3 (CCL7), MIG (CXCL9), M-CSF (CSF1), G-CSF (CSF3), MIG-1a (CCL3), CTACK (CCL27), and IP-10 (CXCL10)." (PMID 34262555, 2021). "CSF1 controls the production, differentiation and function of macrophages and its overexpression may contribute to the acute inflammatory response observed in severe COVID-19." (PMID 33194826, 2020). "In patients with severe COVID-19, a high correlation was observed between circulating inflammatory cytokines, such as IL-6, CXCL10 (IP-10), and CSF1 (M-CSF), and arginine metabolism as well as tryptophan metabolism." (PMID 39759510, 2024). "Together, these results support a specific role for monocyte/macrophage immunopathology in COVID-19 and prioritize the investigation of MCP-3/CCR2 and CSF-1 signaling as therapeutic targets." (PMID 34710339, 2022). "Eight ISGs were downregulated in Asymptomatic as compared with severe COVID-19 cases; CNP, CSF1, IRF1, IFITM10, IRF2BP2, IRF2BPL, SLC25A28 and SOCS3." (PMID 34824360, 2021). "Notable UPRs of COVID-19 blood included IFNA, IFNG, multiple growth factors and ligands, HIF1A, CSF1 and CSF2." (PMID 33782412, 2021). "In the context of severe COVID-19, this molecule influences the CSF1 gene (colony-stimulating factor 1 or macrophage colony-stimulating factor), which may result in increased recruitment of macrophages and an intensified inflammatory response." (PMID 39795977, 2024).
COVID-19 (continued). "Based on our gene expression analysis, all genes except CSF1 were higher in patients who had COVID-19, regardless of COVID-19 severity." (PMID 39205185, 2024). "To conclude, our results suggest that the miR-1207-5p family may interact with SARS-CoV-2 viral genome leading to deregulation of CSF-1, which may enhance inflammatory responses in COVID-19 patients, and promoting EMT, which can contribute to pulmonary fibrosis, a possible sequela of COVID-19." (PMID 33194826, 2020).